EGF (epidermal growth factor)
Diseases named in the same sentence as EGF in open-access papers (continued):
Sharing a sentence is not in itself a finding about the gene and the disease.
tumor (continued). "As shown in the tumor growth curve and the weight assay of collected tumors on the final day, EGF alone did not alter the tumor growth ability, but combination therapy resulted in a significant inhibition of tumor growth in vivo." (PMID 36316307, 2022). "In non-tumor cells, EGFR-OSMR can be activated synergistically by the ligands EGF and OSM." (PMID 35954323, 2022). "In addition, EGF upregulates the expression of ICAM-1 and ɑMβ2 integrin in TAMs and facilitates the interaction between TAMs and tumor cells to form spheroids." (PMID 36532066, 2022). "In addition, EGF, which activates the AKT signaling pathway and enhances tumor growth, invasion, and metastasis, recovered the CD44V3 knockdown-inhibited cell viability." (PMID 36292918, 2022). "After cell straining and centrifugation, cell suspensions consisting of tumor cells and various non-neoplastic stromal cells, were transferred to uncoated culture flasks after which EGF/FGF2 supplemented medium was added." (PMID 36269546, 2022). "In addition, the epidermal growth factor (EGF), hepatocyte growth factor (HGF) and platelet- derived growth factor (PDGF) produced by neutrophils can facilitate tumor progression." (PMID 35711434, 2022). "There was an Arg-Gly-Asp sequence in NH2-terminal epidermal growth factor (EGF)–like domains of MFG-E8, which could bind with αvβ3 and αvβ5 integrins that were usually overexpressed in some tumor cells." (PMID 35597930, 2022). "The increased MUFA in negative LVI indicates an accelerated conversion from excess SFA for membrane phospholipid synthesis and epidermal growth factor signalling, while a reduced MUFA observed in positive LVI due to the export of SFA via tumour cells crossing the lymphatic vasculature." (PMID 33270144, 2021). "In BxPC-3 tumor cells, we detected EGFR trafficking to EEA1-positive early endosomes in all conditions tested, but colocalization was much more evident in cells treated with EGF or EGF and erlotinib (see arrows), in which EGFR was undergoing endocytosis." (PMID 34572731, 2021). "M2-like macrophages promote tumor angiogenesis by producing proangiogenic growth factors (VEGF-A, epidermal growth factor (EGF), and fibroblast growth factor (FGF)), proangiogenic CXC chemokines (CXCL8/IL-8 and CXCL12), and angiogenesis-related factors (TGF-β and TNF-α)." (PMID 34294146, 2021). "They gather in tumor sites and secrete growth-promoting factors like VEGF and EGF." (PMID 34485117, 2021). "TAMs secrete effector cytokines such as epidermal growth factor (EGF), platelet derived growth factor (PDGF), basic fibroblast growth factor (bFGF), hepatocyte growth factor (HGF) and TGF-β, which can promote tumor cells proliferation and survival, based on a huge number of animal studies." (PMID 34368156, 2021). "For example, TAMs are essential for the angiogenesis of the tumor area by secreting VEGF and EGF." (PMID 34580284, 2021). "On the other hand, EGF treatment alone induced strong EGFR degradation in hNDF but not in tumor cells (lane 2), which express much higher EGFR levels than hNDF." (PMID 34572731, 2021). "This optimised OC medium that consists of EGF, BMP2, nicotinamide and inhibitors of ROCK and TGF-β allows long-term culture of HGSC organoids that maintain key histological and morphological characteristics of the tumours of origin." (PMID 33580825, 2021). "Our findings are in accordance with the previous statements, as we found that both ADMSC and mature adipocytes secrete factors that could contribute to tumor development like IL6, EGF, PTGS2 and IL4 in ADMSC, and CCL5, IL1β and IGF in adipocytes." (PMID 33801973, 2021). "One study, during proteomic analysis, found exosome having proteins like VEGF, MCP-1, IL-4, and EGF—they aid tumour cells survival, growth, and transit—those exosomes with TGF-β stimulated division of fibroblasts into myofibroblasts, supporting tumour proliferation, vascularisation, and metastasis." (PMID 34336101, 2021).
tumor (continued). "SPINK1 modulated tumor malignancies and induced the activation of the downstream signaling of epidermal growth factor receptor (EGFR) in cancer cells, due to the structural similarity with epidermal growth factor (EGF)." (PMID 33916984, 2021). "In the chick CAM model, knocking down integrin β5 expression prevents EGF-induced pulmonary metastasis but not primary tumor weight." (PMID 34976811, 2021). "TNF-α is produced by activated monocytes/macrophages, that promote cell proliferation and differentiation and also synergize with epi-epidermal growth factor and insulin to promote the expression of the EGF receptor and produce growth factor-like effects on some tumor cells." (PMID 33494759, 2021). "EGF-stimulated EGFR phosphorylation induces the S100A2 expression, and S100A2 exhibits antitumor activity by reducing the rate of tumor growth when overexpressed in nude mice with NCI-H2172 cell tumor xenograft model." (PMID 34239729, 2021). "In turn, the TAMs can block antitumor immune responses and accelerate tumor progression by increasing the expression of cytokines and chemokines, such as platelet-derived growth factor (PDGF), epidermal growth factor (EGF), and insulin-like growth factor (IGF)." (PMID 34899747, 2021). "TME cells may release growth factors and cytokines such as WNT, epidermal growth factor, TNF, IL-17, and IL-6 in response to therapy-induced tumour cell death, which promotes the survival of residual tumour cells and leads to treatment resistance." (PMID 35003085, 2021). "Growth factors, such as epidermal growth factor (EGF), platelet-derived growth factor (PDGF), pro-inflammatory cytokines, tumor necrosis factor (TNF), tumor promoters, bile acids and ultraviolet B irradiation, are involved in the stimulation of COX-2 expression." (PMID 34640461, 2021). "When EGF activates epidermal growth factor receptor (EGFR), the downstream signaling pathways such as PI3K/AKT and MAPK/ERK can be stimulated, which further confer important roles in metastasis and tumor progression." (PMID 33462201, 2021). "Our previous study found that EBV infection can activate epidermal growth factor (EGF)-induced, SOCE-mediated Ca2+ signaling and increase VEGF production to promote NPC tumor angiogenesis and blocking SOCE using SKF96365 or 2-aminoethoxydiphenyl borate can inhibit the growth and angiogenesis of NPC." (PMID 34684224, 2021). "Moreover, decorin competes with the natural ligand of EGFR, the epidermal growth factor (EGF), and the decorin-EGFR interaction results in internalization and degradation of the receptor via caveolar endocytosis, thus controlling tumor growth." (PMID 34917515, 2021). "Since 2004, conventional chemotherapy is combined with targeted monoclonal antibody therapies specifically directed against vascular endothelial growth factor (VEGF) and epidermal growth factor (EGF) and their receptors to block angiogenic and proliferative tumor actions." (PMID 34924998, 2021). "Normally, tumor promoters (e.g., phorbol ethers or epidermal growth factor (EGF)) themselves are not mutagens or carcinogens." (PMID 34677457, 2021). "In tumor angiogenesis, various pro-angiogenic signals such as vascular endothelial growth factor (VEGF), epidermal growth factor (EGF), and transforming growth factor (TGF) are released to induce the formation of blood vessels and to support tumor proliferation." (PMID 33546106, 2021). "Notably, it has been shown that S1P promotes the production and secretion of growth factors EGF, PDGF, and VEGF and transactivates EGF/IGF receptor signaling pathways, promoting GBM cell proliferation and tumor growth." (PMID 34201962, 2021). "However, more importantly, current anti-angiogenic cancer therapies targeting VEGF-A are confronted with resistance due to upregulation of other growth factors, such as FGF-2, EGF and PDGF by tumor cells." (PMID 34680238, 2021).
tumor (continued). "Moreover, S1P has been shown to transactivate EGF/IGF receptor signaling pathways, resulting in increased GBM cell proliferation and tumor growth." (PMID 34201962, 2021). "Moreover, the GO analysis revealed that most of the angiogenic growth factors and their receptors involved in tumor progression, including VEGF, EGF, EGFR, and FGF, were differentially expressed." (PMID 33803224, 2021). "Similarly, TAMs induce expression mesenchymal markers in cancer cells, primarily at the tumor–stroma interface, by secretion of either TGF-β, IL-8 or EGF." (PMID 34072345, 2021). "However, factors, such as HGF, EGF, PDGF, and TGFβ, released by cells surrounding the tumor are considered to be very important in this process." (PMID 33540535, 2021). "Further studies confirmed higher tumor expression and plasma levels of IL-8, TGF-β1, and TGF-β3, as well as showed other factors’ increases (e.g., epidermal growth factor (EGF), GM-CSF, IFN-α, TGF-β2, and HIF-1α) in the tumor and serum of CRC cachectic patients." (PMID 33557173, 2021). "Emergent cytotoxic activity of EGF in its nanoparticle conjugates is considered as an alternative cancer therapeutics, which conventional EGFR inhibitors have been hampered by the development of drug resistance in some tumor types." (PMID 34512175, 2021). "Histopathological analysis further demonstrated that EGF-targeted NPs inhibited tumor growth to a greater extent than non-targeted or non-NP treatments." (PMID 32345258, 2020). "Because of its ability to bind EGFR, nimotuzumab can competitively interfere with the binding of EGF to EGFR, resulting in the blockade of downstream signaling pathways, inhibiting tumor cell proliferation, promoting tumor cell apoptosis, and enhancing the efficacy of radio- and/or chemotherapy." (PMID 32850421, 2020). "Finally, compared to macroH2A1 KD Huh-7 cells, FAK KD cells exhibited a significant reduction (p < 0.01) in the mRNA levels of tumor-promoting genes CCL2, EGF, BAX, KRT19, EGFR, NOTCH1, ABL1, and SMAD3." (PMID 33182805, 2020). "In the present study, we demonstrate that EGF released from residual tumors induces the activation of EGFR in vascular endothelial cells and stimulates vessel formation, eventually leading to angiogenesis and tumor relapse." (PMID 32630838, 2020). "These cells establish a favorable environment for tumor development by releasing cytokines (IL-6, IL-10 and TGF-β), metalloproteinases (MMP3 and MMP9) and growth factors (HGF, EGF, CTGF and IGF-1), leading to immunomodulation, angiogenesis, invasion, proliferation and tumor cell survival." (PMID 32899449, 2020). "Furthermore, tumour‐promoting growth factors from TAMs, like EGF (epidermal growth factor), also facilitate to formation of vascular tissues and modulate immune response." (PMID 32596949, 2020). "Macroscopically, this study suggests a tumor volume reduction immediately after the treatment with EGF-conjugated GNPs combined with laser irradiation, without showing any skin burn." (PMID 33353068, 2020). "As with the tumor itself, TME also responds to RT by inducing the release of pro-inflammatory cytokines and other molecules, including PDGF, IL1β, TNFα, TGFβ, C-X-C motif chemokine 12 (CXCL12), MMPs, IL6, EGF, and VEGF." (PMID 32660072, 2020). "Furthermore, growth factors such as EGF, IL‐1, TGF can stimulate the mobility of the tumour cells, which is critical in tumour invasion and metastasis." (PMID 32515024, 2020). "In addition, MDSCs secrete IL-6, TGF-β, EGF and HFG to promote epithelial-mesenchymal transition (EMT) in tumor cells." (PMID 31980023, 2020). "Subsequent cultivation within Dulbecco’s Modified Eagle’s Medium/Ham’s -F12 supplemented with epidermal growth factor (EGF), fibroblast growth factor 2 (FGF-2), B27 and 10% fetal calf serum (FCS) led to an adherently growing cell culture for both tumor tissue samples." (PMID 32927768, 2020).
tumor (continued). "Epidermal growth factor, latrophilin and seven transmembrane domain-containing protein 1 (ELTD1) is up-regulated in tumor endothelial cells in many types of cancer and may be a putative predictive biomarker due to its association with ongoing angiogenesis." (PMID 32321460, 2020). "Comparing EGF-treated MDA-MB-468 and MDA-MB-231 cells transfected with Vim Si1 in vitro before injection, we observed a clear diminution of human tumor cell content in lungs after vimentin silencing, as quantified by RT-qPCR." (PMID 32152404, 2020). "In mice with A-431 xenografts, PCI of rGel-EGF caused reduced tumor growth, and, in mice with SCC-026 xenografts, reduced tumor perfusion and increased necrosis induction was observed after PCI of rGel-EGF as compared with control mice receiving PDT or rGel-EGF alone." (PMID 31936595, 2020). "The epidermal growth factor (EGF) family of receptor tyrosine kinases (HER1–4) are activated by ligand-dependent homo-/heterodimerisation and regulate cellular proliferation and tumor progression." (PMID 32782013, 2020). "TAMs participate in the tumour angiogenesis by secreting pro‐angiogenic factors, including VEGF‐A, EGF, PlGF, TGF‐β, TNF‐α, IL‐1β, IL‐8, CCL2, CXCL8 and CXCL12, and enable tumour metastasis by up‐regulated N‐cadherin and Snail, whereas down‐regulated E‐cadherin." (PMID 32588948, 2020). "The other studies showed multiple cytokines exist in tumor microenvironment, such as transforming growth factor (TGF-), epidermal growth factor (EGF), Insulin-like growth factor (IGF), vascular endothelial growth factor (VEGF) drive cross-talk between tumor cells and stromal cells." (PMID 32774840, 2020). "Furthermore, activating transcription factor 6 (ATF6) induced the upregulation of EGF, and its antagonism effectively suppressed these SCC-mediated events and inhibited tumor recurrence after chemotherapy." (PMID 32630838, 2020). "Moreover, the EGF produced by tumor cells stimulated the secretion of CSF1 by cells of the microenvironment, which amplified proliferation of tumor cells." (PMID 31938054, 2020). "First, we consider that the dormancy of tumor cells is mediated exclusively by the lack of EGF and the exposition to type II IFN, which is secreted by CD8+ T-cells." (PMID 31157216, 2019). "However, in patient 1, by comparing three different tumor sections, expression of EGF was lower than in VEGF for peripheral than central and basal sections of tumor." (PMID 31565199, 2019). "In our in vivo model of xenografts, mouse fibroblasts could be further activated by celecoxib-induced secretion of EGF and AREG by epithelial tumor cells and by a stress environment characteristic of castration-resistant cells." (PMID 31816863, 2019). "Moreover, basal EGF secretion by CAFs and in the CAF/tumor cell coculture system was dose-dependently decreased by imatinib." (PMID 30710055, 2019). "M2 macrophages have an important role during cancer development as a source of growth factors (EGF and VEGF) that proliferate tumor growth and angiogenesis, anti-inflammatory cytokines that control epithelial cells proliferation and wound healing, as well as proteases that promote tumor metastasis." (PMID 31632482, 2019). "In addition, it has been reported that crosstalk between EGF and VEGF-A signaling exists in tumor growth." (PMID 31717527, 2019). "Moreover, epidermal growth factor (EGF) derived from activated fibroblasts inside the compact MU microenvironment further sustains ATC ITGA5 expression, which strengthens tumor–stromal interaction inside MUs." (PMID 30710055, 2019). "Epidermal growth factor (EGF) could protect TRAIL sensitive HEK293 and MDA-MB-231 tumor cells for apoptosis involving Akt activation and inhibition of mitochondrial apoptosis." (PMID 31333662, 2019).
tumor (continued). "When VX2 cells and MSCs were co-inoculated in group control 1, the ROD values of TGFβ1 and EGF were both significantly increased (0.899±0.124, 1.053±0.107), which indicated that MSCs facilitated the expression of these two growth factors in VX2 tumor tissue." (PMID 31528217, 2019). "Thus, EGF, IGF1, FGF, HGF, or PDGF, which are normally found in the tumor microenvironment, signal EMT through their receptors in cancer cells." (PMID 31554173, 2019). "Macrophages in the peritoneum support angiogenesis and tumor growth by producing VEGF and EGF." (PMID 31632482, 2019). "In addition to EGF, IL-6 is another oncogenic cytokine, and its activation can induce STAT3 and AKT signaling, resulting in tumor growth and invasion in numerous cancers, including cervical." (PMID 31235851, 2019). "TAMs produce growth and survival factors for tumor cells (e.g., EGF, fibroblast growth factor [FGF], IL-6, and IL-8) and angiogenic factors (EGF, FGF, vascular endothelial growth factor [VEGF], PDGF, TGF-β, and CXC chemokines) and suppress the T-cell dependent antitumor immunity." (PMID 31277406, 2019). "Considering the roles of E2, EGF, and Notch involved in the regulation of FTE homeostasis, dysfunction of these factors may transform the FTECs into tumor cells, which are the basis for HGSC." (PMID 31430961, 2019). "Factors are involved in stimulating tumor angiogenesis indirectly by inducing VEGF, TGF-α and β, TNF-α, keratinocyte growth factor, insulin-like growth factor I (IGF-I), FGF, PDGF, and cytokines [interleukin (IL)-1α and IL-6 and EGF on tumor cells]." (PMID 31303863, 2019). "In vitro assays highlighted the greater effectiveness of RSV/DXT loaded EGF LPNs in decreasing the viability of tumor cells (HCC827 and NCIH2135) in comparison to RSV/DXT loaded LPNs, thus confirming the usefulness of including the targeting moiety EGF in the NP." (PMID 31349656, 2019). "In middle stage LADC, receptor EGFR can be activated by interacting with ligands EGF, which may be secreted by nearby macrophage stimulated by hypoxia, and BGN, which may be secreted by tumor endothelial cells." (PMID 31217907, 2019). "55, the tumor does not develop and will be eliminated within few weeks depending on the available concentration of the EGF." (PMID 31157216, 2019). "Contrary, M2 TAM are activated with transforming growth factor beta (TGF-β), interleukin 4(IL-4) and interleukin 13 (IL-13) to release a set of growth factors: VEGF, epidermal growth factor (EGF), and fibroblast growth factor (FGF); thus promoting angiogenesis and tumor growth." (PMID 30680411, 2019). "Through its epidermal growth factor (EGF) domains, MUC4 may act as an intramembrane ligand for receptor tyrosine kinase ErbB2 and execute antiapoptotic function and by that promote tumor progression." (PMID 31091244, 2019). "By influencing the tumor microenvironment and the immune system, blocking the expression of COX-2 and the proto-oncogene c-FOS and interfering with the EGF/EGFR pathway, they are able to reduce inflammation, inhibit tumor cell growth, induce apoptosis, and cause autophagy." (PMID 30987191, 2019). "In addition, NAB2 upregulation in EGF-treated FaDu cell diminishes EGR1 transcriptional activity, resulting in the upregulation of Sp1-dependent tumor-promoting genes." (PMID 30845713, 2019). "EGF has been reported to induce MYCN expression and to favor tumor growth." (PMID 31013771, 2019). "Using precision-cut 250 μm x 6 mm slices grown on a solid support platform, we compared tumor slices that were placed in complete growth media containing 10 ng/mL EGF with and without JMV." (PMID 31489118, 2019). "Co-expression had a key impact on tumor evolution and diverse PE profiles led to draw the heterogenic classification, as the personalized/complementary insight in the functional behavior of VEGF and EGF." (PMID 31565199, 2019).